HDAC5 (histone deacetylase 5)
Diseases named in the same sentence as HDAC5 in open-access papers (continued):
Sharing a sentence is not in itself a finding about the gene and the disease.
status epilepticus (1 paper, 2016). Status epilepticus is defined as a continuous seizure lasting more than 30 min, or two or more seizures without full recovery of consciousness between any of them. "Notably, the increased expression of HDAC5 mRNA with a maximum 12 h after KA injection clearly parallels highest seizure activity during the acute status epilepticus, which was maximal after 6–12 h." (PMID 26603269, 2016). "On the other hand, increases in HDAC5 expression and decreases in HDAC7 expression during the acute status epilepticus may have a role in regulating expression of seizure‐related genes by specifically acetylating histones." (PMID 26603269, 2016).
thymic carcinoma (1 paper, 2023). Thymic carcinoma (TC) is a type of thymic epithelial neoplasm characterized by a high malignant potential. "Epithelial rich TETs (namely B3-type and thymic carcinomas) displayed positive cytoplasmic HDAC5 staining more often (Fisher’s exact test, p = 0.022, 37% vs. 13%), and a higher cytoplasmic HDAC5 H-score, compared to the rest of the WHO types (Mann–Whitney, p = 0.002, median value 160 vs. 20)." (PMID 36901692, 2023).
thymic epithelial tumors (1 paper, 2023). "In this study we attempt the first comprehensive evaluation of six class I (HDAC1, HDAC2, HDAC3) and II HDACs (HDAC4, HDAC5, HDAC6) expression patterns in thymic epithelial tumors (TETs), with the aim of identifying their possible association with a number of clinicopathological parameters." (PMID 36901692, 2023).
Ureteral obstruction (1 paper, 2021). Obstruction of the flow of urine through the ureter. "In the present study, we first revealed that HDAC5 expression was increased in renal tubular cells of diabetic mice, fibrosis region of unilateral ureteral obstruction (UUO) mice, and in vitro high glucose-cultured human renal tubular cell line (HK2)." (PMID 33414476, 2021).
Waldenström macroglobulinemia (1 paper, 2024). "Both miRNAs regulate HDAC5 levels in non-malignant neural cells, and miR-9 is also involved in HDAC5 regulation in Waldenström macroglobulinemia, a B-cell low-grade lymphoma." (PMID 38369747, 2024).
tumor (69 papers, 2006 to 2025). "Tumour cell line sensitivity to kinase inhibitors was associated with upregulation of HDAC5, HDAC1, and several SIRT genes." (PMID 38369747, 2024). "Tumor tissue also expressed high levels of the histone deacetylase HDAC5 and the SUMO/ubiquitin E3 ligase TRIM28, which is linked to STAT3 signaling, as well as low expression of the tumor suppressor PTGIS." (PMID 30645971, 2019). "Consistently, high HDAC5 expression was significantly associated with poor overall survival, implicating it as a novel marker for risk stratification and its role in tumor cell growth." (PMID 24191246, 2013). "Moreover, the cytoplasmic H-score of all three class II HDACs was higher in epithelial rich TETs (B3, C) and increased in more advanced tumor stages, while in the case of HDAC5 it was also associated with disease recurrence." (PMID 36901692, 2023). "Notably, we demonstrated for the first time that the upregulation of HDAC5 caused by S. maltophilia infection is associated with tumor progression, supporting a causal role in the process of lung tumor growth." (PMID 36819033, 2023). "The results showed that inhibiting HDAC5 significantly increased CD8+ T cell infiltration in the tumor microenvironment, reduced the proportion of Tregs, and exhibited synergistic effects with anti-PD-1 antibodies, jointly inhibiting tumor growth." (PMID 40657246, 2025). "For instance, the expression of writers such as EHMT2, readers such as BRD4, or erasers such as HDAC5 is high in tumor tissues." (PMID 39774014, 2025). "Recently, a study identified a novel histone deacetylase 5 (HDAC5)-CCL2/CCR2-TGF-β/SMAD4 axis driven by epigenetic regulation to promote tumor growth in a PDAC model." (PMID 38167055, 2024). "HDAC5 inhibition led to increased PD-L1 expression, and thus sensitized tumor cells to immune checkpoint blockade." (PMID 38672128, 2024). "The MDA-MB-231 cell line has been widely used as a model in studies of the role of HDAC5 in cancer and of its effect on tumour responses to a variety of antitumor agents." (PMID 38369747, 2024). "Mechanistically, HDAC5 in tumor cells inhibits Socs3, a negative regulator of CCL2, resulting in a shift from neutrophils to CCR2-expressing macrophages." (PMID 38167055, 2024). "These associations are contrary to prior reports which found the benefits of downregulating HDAC5 in tumours and detrimental effects of HDAC5 upregulation on tumour progression." (PMID 38369747, 2024). "KAT7, for example, inhibits tumor cell proliferation and invasion by acetylating H4K5 at promoters of FOXO1 and FOXO3a genes, and HDAC5 loss increased H3K27-ac acetylation and circumvented oncogene-related cell cycle repression." (PMID 37789275, 2023). "To characterize the correlation between the expression of a potential target gene, HDAC5, and miR-4256, we examined HDAC5 mRNA in tumor tissues in nude mice by RT‒qPCR." (PMID 37415735, 2023). "HDAC5 silencing or inhibition augmented the ability of anti-PD-1 therapy to increase the levels of tumor-infiltrating CD8+ T cells and prolong the survival of tumor-bearing mice." (PMID 35265200, 2022). "In conclusion, we report a previously uncharacterized role of HDAC5 in enhancing tumor immunity by repressing NF-κB-mediated PD-L1 expression." (PMID 35265200, 2022). "Consistent with our study, HDAC5 was also found to promote the proliferation and migration of various cells, such as tumor cells 37, smooth muscle cells 41 and epithelial cells." (PMID 36263180, 2022). "Whereas HDAC1 and HDAC2 promote UC, HDAC5 is often downregulated and only weakly expressed in UC cell lines, suggesting a tumor-suppressive function." (PMID 35624179, 2022). "HDAC5 showed decreased levels in tumor tissue while HDAC7 was significantly increased in tumor tissue." (PMID 36227941, 2022).
tumor (continued). "HDAC5 was reported to regulate the expression of PD-L1 through direct interaction with NF-κB p65 and inhibition of HDAC5-sensitized tumor cells to immune checkpoint blockade." (PMID 35897717, 2022). "In the Hdac5 knockdown group, anti-PD-1 treatment dramatically increased the tumor infiltration of CD45+CD8+ and CD45+CD4+ T cells as well as decreased the levels of CD11b+Gr1+ myeloid cells and CD4+Foxp3+ Treg cells in tumors." (PMID 35265200, 2022). "Xenograft tumor experiment in nude mice confirmed that METTL3 silencing repressed OS cell proliferation in vivo via the HDAC5/miR-142-5p/ARMC8 axis." (PMID 35396379, 2022). "The Class IIb member, HDAC6, even exhibited contradictory activities to HDAC5 in the regulation of tumor immunity." (PMID 35265200, 2022). "As well known, EMT was the important characteristic of tumor to regulate invasion and metastasis, and HDAC5 was also reported to mediate EMT of tumor cells." (PMID 33414476, 2021). "In four patients, we observed a concordant expression of HDAC5 in the primary tumor and metastasis, and in two cases, an opposite expression pattern was present." (PMID 34204116, 2021). "Downregulation of either CD13 or HDAC5 increased NF‐κB p65 acetylation (Lys310) and degradation, which lead to the decrease tumor growth." (PMID 33377659, 2020). "Supporting a tumor-suppressive function of HDAC5 in UC, its overexpression diminished growth in three out of four cell lines." (PMID 31052182, 2019). "Accordingly, HDAC5 was weakly expressed in UC cell lines suggesting a possible tumor-suppressive function." (PMID 31052182, 2019). "We also found that the transcriptional activation of HDAC5 is partly mediated by HOXC-AS3 in the tumor progression of GC through binding to YBX1, thus facilitating GC cell proliferation and migration." (PMID 30286788, 2018). "HDAC5 expression was investigated in several tumor entities and its oncogenic de-regulation has been found to be dependent on the cancer type." (PMID 30321986, 2018). "Aberrant activation of HDAC5 in tumor cells leads to dysregulation of a diverse set of genes mainly involved in the regulation of proliferation, migration, and angiogenesis." (PMID 30286788, 2018). "Using mouse models with subcutaneous tumor xenografts grown from implanted A375 cells, we observed smaller tumors from A375 cells expressing ShRNA against HDAC5 or HDAC6." (PMID 26747087, 2016). "Analyses of the quantified images indicated that the differences between tumor and normal tissues in total HDAC5 or HDAC6 levels protein levels (P < 0.0001) were all highly significant when comparing the 33 tumor samples with the 31 normal skin samples." (PMID 26747087, 2016). "We further investigated the effects of HDAC5 or HDAC6 knockdown on A375 cells tumor growth when the cells were transplanted subcutaneously." (PMID 26747087, 2016). "At 12 h treatment, gefitinib induced the expression of HDAC5, a growth inhibitory tumor suppressor and pro-apoptotic factor, in Hec50co cells, while regulators of cell migration and morphogenesis such as GIT1 and CALD1 were down-regulated by gefitinib." (PMID 20579378, 2010). "Similarly, miR-589-5p negatively affects HDAC5 levels, and upregulation of mir-589-5p in tumour cells by 5-aza-2-deoxycytidine downregulated HDAC5." (PMID 38369747, 2024). "For example, both overexpression and downregulation or loss of HDAC2 and HDAC5 have been reported in tumours, and both types of changes were associated with negative outcomes." (PMID 38369747, 2024). "Endogenous IP assays confirmed the interaction between SNRNP200 and HDAC5 in MPS2 tumor cells." (PMID 39285160, 2024). "The three class II HDACs (HDAC4, HDAC5, HDAC6) exhibited similar expression patterns, with predominantly cytoplasmic staining, that was higher in epithelial rich TETs (B3, C) and more advanced tumor stages, while it was also associated with disease recurrence." (PMID 36901692, 2023).
tumor (continued). "To further investigate the role of HDAC5 in a model mimicking the mutational burden in human PDAC, we generated a mouse PDAC model using genetically engineered KPC mouse (KrasG12D/+; LSLTrp53R172H/+; Pdx-1-Cre) derived tumor cells." (PMID 35265200, 2022). "In the Hdac5 knockdown group, anti-PD-1 treatment strongly suppressed tumor growth." (PMID 35265200, 2022). "The role of HDAC5 in cancer remains controversial; HDAC5 may act as a tumor suppressor or oncogene in a tissue-specific or tumor subtype-dependent manner 15-17." (PMID 35265200, 2022). "Therefore, the correlation between HDAC5 and p65/NF-κBsignaling during tumor progression has drawn researchers’ attention." (PMID 34178647, 2021). "Here, HDAC4 and HDAC5 were shown to mediate the regulation of AMPK on tumour metabolism." (PMID 32519437, 2020). "With regard to both HDAC5 as well as HDAC7 expression, we found significant differences between D3 vs. M3 tumours for only one of the two probes that had been used (HDAC5 probe 1 p = 0.90, HDAC5 probe 2 p = 0.004, HDAC7 probe 1 p = 0.30, HDAC7 probe 2 p = 0.02)." (PMID 33316946, 2020). "The results suggest that HDAC4 and HDAC5 might play a mediating role in AMPK regulation of tumour cell metabolism." (PMID 32519437, 2020). "Taken together, these findings suggest a possible tumor-suppressive function of HDAC5 in UC." (PMID 31052182, 2019). "HDAC5 or HDAC6 knockdown dramatically inhibited tumor growth, especially HDAC6 knockdown, indicating that HDAC6 may have a more serious influence on cancer cell growth." (PMID 26747087, 2016). "Another study showed that overexpression of HDAC5 is related to upregulated CD70, which induces the growth suppression and apoptosis of tumor cells, indicating that targeting HDAC5 may regulate the immune response and affect tumor progression in cancer immunotherapy." (PMID 35585975, 2022). "Altogether, our study showed the tumor inhibition effect of DHX9-HDAC5-BECN1 axis in ER+ and TNBC cell lines, implying the therapeutic potential of DHX9 or HDAC5 inhibitors in at least HR+ or TNBC subtypes." (PMID 40659605, 2025). "Specifically, HDAC4, HDAC5, KAT2B, NCOA1, SIRT1, and SIRT4 had lower expression in tumor tissues across 14, 12, 18, 17, 16, and 12 cancer types, respectively." (PMID 39906742, 2024). "For example, HDAC5 depletion in MCF-7 and HeLa cells using HDAC5 siRNA improved tumour sensitivity to the DNA damaging agents doxorubicin and cisplatin." (PMID 38369747, 2024). "The HDAC5 gene is a member of the HDAC family of enzymes, and plays vital roles in the tumor progression of multiple human cancers including GC." (PMID 37415735, 2023). "Increases in HDAC activity, as our ATAC-seq data suggest for HDAC5 and HDAC9 in JMML spleen HSPCs, have been identified in a variety of tumor types." (PMID 37958378, 2023). "Studies have shown that genome-wide histone acetylation levels are generally reduced in tumor cells, among which HDAC1, HDAC5 and HDAC7 are regarded as tumor markers." (PMID 35545840, 2022). "Studies have shown that formononetin combination therapy reverses adriamycin-induced epithelial-mesenchymal transformation (EMT) of tumor cells and prevents EMT by inhibiting HDAC5, thereby enhancing the therapeutic effect of adriamycin on GBM cells." (PMID 36046228, 2022). "Overexpression of HDAC5 is related with upregulated CD70, inducing growth suppression and apoptosis of tumor cells." (PMID 35585975, 2022). "Histone deacetylase 5 (HDAC5)-induced bypass promotes macrophage recruitment into the TME and enables tumor recurrence following the extinction of KRAS (G12D)." (PMID 35922812, 2022). "Tumours that escape treatment trough HDAC5, showed a prominent neutrophil-to-macrophage phenotype as compared to oncogenic KRAS-driven tumours." (PMID 33671588, 2021).
tumor (continued). "In addition, HDAC5 also inhibits the proliferation of tumor cells, which may be mediated by TGF-β." (PMID 34880761, 2021). "HDAC1 (p = 0.05), HDAC3 (p = 0.02), the second probe of HDAC5 (p = 0.04) and of HDAC7 (p = 0.03), and HDAC8 (p = 0.004), were increased in tumours with 8q gain, while HDAC11 was decreased (p = 0.002)." (PMID 33316946, 2020). "We suggest that a key intermediate must exist between HDACs and HK2, mediating the regulation of HK2 expression levels and tumour metabolism by HDAC4 and HDAC5." (PMID 32519437, 2020). "HDAC5 or HDAC6 knockdown in A375 cells induced apoptosis, arrest of cell cycle and tumor growth in nude mice." (PMID 26747087, 2016). "HDAC5 and HDAC6 knockdown induced a 25 and 98 % reduction in the tumor volume of A375 cells, respectively." (PMID 26747087, 2016). "Alterations in the tumor immune microenvironment can also lead to primary drug resistance, such as the finding that tumor-associated macrophages can be recruited due to the effect of HDAC5 on chemokine, mediating SMAD4-dependent and KRAS-independent PDAC tumor growth." (PMID 36675641, 2023). "In addition, an expanded sample size including 519 tumor samples of HNSC and 44 normal tissue samples was adopted to examine the expression of HDAC5 in the GEPIA online database." (PMID 36910848, 2023). "HDAC5 inhibits suppressor of cytokine signaling 3 (SOCS3), which leads to an increase of C-C motif chemokine ligand 2 (CCL2), recruits CCR2+ macrophages, promotes macrophages to reaggregate into tumor microenvironments, and promotes tumor recurrence." (PMID 34880761, 2021). "Moreover, the expression of HDAC5 and HDAC11 are positively parallel with tumor stage and grade, T, N, and M stage." (PMID 34308568, 2021). "HDAC5 has been reported to repress the production of proinflammatory cytokine in macrophages via TNF-α signaling and play an inhibitory role in regulating tumor microenvironments." (PMID 34880761, 2021). "We found consistent results with tumor growth after injecting scramble A375 cells for 3 weeks; the null mice (n = 10) group lost four mice, whereas the HDAC5 or HDAC6 knockdown groups had no mice dead." (PMID 26747087, 2016). "Science MMP9 promotes tumor invasion and metastasis through extracellular matrix remodeling, regulation of cell adhesion, and degradation of vascular basement membrane and perivascular matrix during EMT, the correlation between HDAC5 and EMT during tumorigenesis has drawn a great attention." (PMID 34178647, 2021).